RXRA (retinoid X receptor alpha)
Description:
Receptor for retinoic acid that acts as a transcription factor. Forms homo- or heterodimers with retinoic acid receptors (RARs) and binds to target response elements in response to their ligands, all-trans or 9-cis retinoic acid, to regulate gene expression in various biological processes. The RAR/RXR heterodimers bind to the retinoic acid response elements (RARE) composed of tandem 5'-AGGTCA-3' sites known as DR1-DR5 to regulate transcription. The high affinity ligand for retinoid X receptors (RXRs) is 9-cis retinoic acid. In the absence of ligand, the RXR-RAR heterodimers associate with a multiprotein complex containing transcription corepressors that induce histone deacetylation, chromatin condensation and transcriptional suppression. On ligand binding, the corepressors dissociate from the receptors and coactivators are recruited leading to transcriptional activation. Serves as a common heterodimeric partner for a number of nuclear receptors, such as RARA, RARB and PPARA. The RXRA/RARB heterodimer can act as a transcriptional repressor or transcriptional activator, depending on the RARE DNA element context. The RXRA/PPARA heterodimer is required for PPARA transcriptional activity on fatty acid oxidation genes such as ACOX1 and the P450 system genes. Together with RARA, positively regulates microRNA-10a expression, thereby inhibiting the GATA6/VCAM1 signaling response to pulsatile shear stress in vascular endothelial cells. Acts as an enhancer of RARA binding to RARE DNA element. May facilitate the nuclear import of heterodimerization partners such as VDR and NR4A1. Promotes myelin debris phagocytosis and remyelination by macrophages. Plays a role in the attenuation of the innate immune system in response to viral infections, possibly by negatively regulating the transcription of antiviral genes such as type I IFN genes. Involved in the regulation of calcium signaling by repressing ITPR2 gene expression, thereby controlling cellular senescence.
Synonyms: NR2B1; RXRalpha; RXR-alpha
Tractability: Small molecule: an approved drug acts on it; a structure with a bound ligand is known; a high-quality ligand is known; it has a high-quality binding pocket; it belongs to a druggable protein family. PROTAC: UniProt records ubiquitination sites on it; ubiquitination databases record sites on it; a small molecule that binds it is known.
Target class: Nuclear hormone receptor subfamily 2 group B member 1; Nuclear hormone receptor subfamily 2; Nuclear hormone receptor subfamily 2 group B; Nuclear receptor; Transcription factor
Chemical probes: CHEMBL101661, CHEMBL80236, JP3000, JP3000 (high quality), PD084147, PD134474
Safety:
Unwanted effects reported when the protein is acted on. In parentheses: how it was acted on, where the effect was seen, and who reports it.
anemia (source: ClinPGx)
anemia and neutropenia (source: ClinPGx)
Gene: Protein-coding gene on chromosome 9 (134,317,098 to 134,440,585, forward strand). Ensembl gene ENSG00000186350.
Subcellular location: Nucleus; Cytoplasm; Mitochondrion
Subcellular location (Human Protein Atlas): Nucleoplasm; Golgi apparatus
Pathways (Reactome):
Metabolism: Activation of gene expression by SREBF (SREBP); Carnitine shuttle; Endogenous sterols; PPARA activates gene expression; Recycling of bile acids and salts; Regulation of lipid metabolism by PPARalpha; Synthesis of bile acids and bile salts; Synthesis of bile acids and bile salts via 27-hydroxycholesterol; Synthesis of bile acids and bile salts via 7alpha-hydroxycholesterol
Signal Transduction: NR1H2 & NR1H3 regulate gene expression linked to gluconeogenesis; NR1H2 & NR1H3 regulate gene expression linked to lipogenesis; NR1H2 & NR1H3 regulate gene expression linked to triglyceride lipolysis in adipose; NR1H2 & NR1H3 regulate gene expression to control bile acid homeostasis; NR1H2 & NR1H3 regulate gene expression to limit cholesterol uptake; NR1H3 & NR1H2 regulate gene expression linked to cholesterol transport and efflux; Signaling by Retinoic Acid; TGFBR3 expression
Developmental Biology: Activation of anterior HOX genes in hindbrain development during early embryogenesis; Transcriptional regulation of brown and beige adipocyte differentiation by EBF2; Transcriptional regulation of granulopoiesis; Transcriptional regulation of white adipocyte differentiation
Circadian clock: BMAL1:CLOCK,NPAS2 activates circadian expression; Expression of BMAL (ARNTL), CLOCK, and NPAS2; RORA,B,C and NR1D1 (REV-ERBA) regulate gene expression
Cellular responses to stimuli: Cytoprotection by HMOX1; Heme signaling
Gene expression (Transcription): MLL4 and MLL3 complexes regulate expression of PPARG target genes in adipogenesis and hepatic steatosis; Nuclear Receptor transcription pathway
Metabolism of proteins: SUMOylation of intracellular receptors
Organelle biogenesis and maintenance: Transcriptional activation of mitochondrial biogenesis
Gene Ontology:
Molecular function: DNA binding domain binding; DNA-binding transcription factor activity; double-stranded DNA binding; enzyme binding; identical protein binding; LBD domain binding; nuclear receptor activity; nuclear vitamin D receptor binding; peptide binding; protein binding; retinoic acid binding; retinoic acid-responsive element binding; RNA polymerase II cis-regulatory region sequence-specific DNA binding; RNA polymerase II transcription regulatory region sequence-specific DNA binding; sequence-specific DNA binding; sequence-specific double-stranded DNA binding; transcription cis-regulatory region binding; transcription coregulator binding; vitamin D response element binding; zinc ion binding; DNA-binding transcription factor activity, RNA polymerase II-specific; transcription coregulator activity; chromatin DNA binding; DNA binding; nuclear steroid receptor activity; and 2 more
Biological process: cell maturation; cellular response to low-density lipoprotein particle stimulus; hormone-mediated signaling pathway; monocyte differentiation; mRNA transcription by RNA polymerase II; negative regulation of transcription by RNA polymerase II; peroxisome proliferator activated receptor signaling pathway; positive regulation of DNA-templated transcription; positive regulation of lipoprotein transport; positive regulation of thyroid hormone receptor signaling pathway; positive regulation of transcription by RNA polymerase II; positive regulation of vitamin D receptor signaling pathway; response to retinoic acid; retinoic acid receptor signaling pathway; bile acid and bile salt transport; cell differentiation; nervous system development; positive regulation of bone mineralization; positive regulation of cholesterol efflux; positive regulation of lipid metabolic process; regulation of lipid metabolic process; gene expression; nuclear receptor-mediated steroid hormone signaling pathway; regulation of DNA-templated transcription
Cellular component: chromatin; cytoplasm; mitochondrion; nucleoplasm; nucleus; receptor complex; RNA polymerase II transcription regulator complex; transcription regulator complex; cytosol
Genetic constraint (gnomAD): Loss-of-function variants: 5 observed, 39.49 expected, observed/expected ratio (o/e) 0.13, 90% interval 0.065 to 0.27. The upper end of that interval is the gene's LOEUF score, 0.27, which puts it in group 1 of 6, group 1 being the genes least tolerant of losing a copy. Missense variants: 397 observed, 648.27 expected, observed/expected ratio (o/e) 0.61, 90% interval 0.56 to 0.67. Synonymous variants: 287 observed, 273.12 expected, observed/expected ratio (o/e) 1.05, 90% interval 0.95 to 1.16.
Gene-disease validity (ClinGen):
ClinGen rates the evidence that RXRA causes each of these diseases.
congenital heart disease (inheritance undetermined): No Known Disease Relationship. A heart disease that is present at birth.
Cancer hallmarks: escaping immune response to cancer; suppression of growth (promotes); invasion and metastasis (suppresses); tumour promoting inflammation; escaping programmed cell death (suppresses); angiogenesis (suppresses); escaping programmed cell death (promotes); proliferative signalling (promotes)
Homologues: Orthologues: chimpanzee RXRA (99% identical), macaque RXRA (98% identical), mouse Rxra (98% identical), rat Rxra (97% identical), dog RXRA (97% identical), pig RXRA (97% identical), guinea pig RXRA (96% identical), tropical clawed frog rxra (90% identical), zebrafish rxraa (86% identical), zebrafish rxrab (73% identical), Drosophila melanogaster usp (45% identical), Caenorhabditis elegans nhr-41 (31% identical), and 25 more. Paralogues in human: RXRG (71% identical), RXRB (71% identical), NR2F1 (37% identical), NR2F2 (36% identical), HNF4G (35% identical), NR2F6 (34% identical), HNF4A (33% identical), NR2C2 (33% identical), NR2C1 (30% identical), NR2E3 (29% identical), NR2E1 (28% identical).
Diseases named in the same sentence as RXRA in open-access papers:
RXRA is named in the same sentence as 200 diseases in open-access papers, as found by Europe PMC text mining. Sharing a sentence is not in itself a finding about the gene and the disease. The quoted sentences say what the papers report.
breast cancer (45 papers, 2004 to 2025). A primary or metastatic malignant neoplasm involving the breast. "The positive impact of TRα on the BC prognosis is possibly caused by heterodimerization with RXRα in the nucleus of breast cancer cells." (PMID 37509273, 2023). "Six other RXRA CpGs (cg13786567, cg02127980, cg14154547, cg13510651, cg14236758, and cg13941235) also showed evidence of interacting with 25(OH)D to affect breast cancer risk." (PMID 29996894, 2018). "We carried out immunoprecipitation assays to assess whether, firstly, there exists a direct or indirect association between RARα, the RXRα heterodimer and Sin3A in breast cancer cell lines and, secondly, whether MAD1-SID treatment would disrupt this interaction." (PMID 35406744, 2022). "Used off-label for lung and breast cancer and Kaposi’s sarcoma, bexarotene binds to RXRs (RXRα, RXRβ, and RXRγ), activating these ligand-activated transcription factors to regulate gene expression." (PMID 40334012, 2025). "Our findings unravel an unexpected role of transcription factor RXRα in specific miRNA maturation at post-transcriptional level through pre-miRNA binding, and present a mechanistic insight regarding RXRα role in breast cancer progression." (PMID 37735649, 2023). "Nuclear RXRα expression in breast cancer tissue leads to an improved OS, whereas cytoplasmic RXRα expression is significantly correlated with poor outcomes in terms of both OS and DFS." (PMID 37509273, 2023). "Pathophysiologically, the negative effect of RXRα on miR-103 maturation correlates to the positive effects of RXRα on the expression of Dicer, a target of miR-103, and on the inhibition of breast cancer." (PMID 37735649, 2023). "The expression of cytoplasmic RXRα is correlated with more aggressive breast cancer types, whereas nuclear RXRα expression appears to be a protective factor." (PMID 37509273, 2023). "RNA sequencing was used to elucidate the effects of the novel RXRα agonist MSU-42011 on the transcriptome in mammary tumors of HER2+ mouse mammary tumor virus (MMTV)-Neu mice." (PMID 36901727, 2023). "In another study, we were able to show that RXRα and PPARγ are overexpressed in BRCA1 mutated breast cancer cases and predict prognosis." (PMID 35406808, 2022). "In many tumor cells including breast cancer cells, the nuclear receptor RXRα is hydrolyzed by a restricted protease." (PMID 34539418, 2021). "α-Mangostin induces apoptosis, suppresses the migration and invasion of breast cancer cells through the PI3K/AKT signaling pathway by targeting RXRα, and cyclin D1 has involved in this process." (PMID 34539418, 2021). "This is the first retrospective cohort study to define the prognostic role of cytoplasmic versus nuclear expression of RXRα in sporadic mammary cancer using a large clinical patient cohort and a long-term follow-up." (PMID 34359656, 2021). "In breast cancers, RXRα mRNA expression was significantly (p = 0.0000207) lower in the tumor samples than in adjacent normal tissue in 112 paired samples from advanced breast cancer patients." (PMID 34638488, 2021). "Considering the immense development of today’s therapeutic approaches in oncology towards customized therapy, this study aimed to assess the prognostic value of nuclear versus cytoplasmic retinoid X receptor α (RXRα) expression in breast cancer." (PMID 34359656, 2021). "Recent reports show that RXRα is critical for breast cancer progression and has been proven to be a transcriptional factor inducing tumor suppression in breast cancer." (PMID 34376200, 2021). "α-Mangostin induces apoptosis of breast cancer cells through the PI3K/Akt signaling pathway by targeting RXRα, and cyclin D1 has involved in this process." (PMID 34539418, 2021). "No study so far has identified the subcellular localization of RXRα as a prognostic factor in human breast cancer specimens." (PMID 34359656, 2021).
breast cancer (continued). "The aim of this retrospective study was to assess the prognostic value of cytoplasmic versus nuclear RXRα expression in breast cancer (BC) tissue samples and to correlate the results with clinicopathological parameters." (PMID 34359656, 2021). "By western blotting, we determined PPAR, RXRα, coactivator, and cell cycle regulatory protein expression in human breast cancer cell lines." (PMID 21080969, 2010). "Additionally, we showed that the community cohesion scores can be used to predict the drug response and suggested the potential combination therapies (e.g. NADPT or RXRA inhibitors) to reduce tamoxifen resistance for ER+ breast cancer." (PMID 38622359, 2024). "As miRNA has multi-targets, RXRα may affect other target genes of miR-103 to exert its anti-breast cancer effects, which need further investigation." (PMID 37735649, 2023). "Interestingly, the results of our study confirm our former investigation into the subcellular localization of PPARγ and RXRα and its influence on survival in breast cancer patients." (PMID 37509273, 2023). "Interestingly, RXRα was reported to inhibit radioresistance in the Head and Neck Squamous Cell Carcinoma; however, its explicit role in breast cancer remains largely elusive." (PMID 34376200, 2021). "The expression of RXRA also plays a key role in breast cancer." (PMID 31213036, 2019). "RXRA had been reported to play critical roles in breast cancer cell progression." (PMID 30518934, 2018). "Apart from the fact that the role of the PPARG/RXRA heterodimer in urothelial cancer is exchanged with the ESR1 hormone receptor in breast cancer, the key transcription factors FOXA1 and GATA3 are downregulated in the basal/SCC-like subtypes of both tumor types." (PMID 26008846, 2015). "In particular, the present study investigated the RXRα isoform, which has been suggested as a potential therapeutic target in breast cancer cells, due to the observation that overexpression of RXRα sensitized breast cancer cells lines to the antiproliferative effects of RXR-selective ligands." (PMID 25778982, 2015). "Moreover, synergistic or additive effects of growth inhibition between PPARγ and RXRα agonists have been found in liposarcoma and breast cancer cells." (PMID 15467764, 2004). "For breast cancer, there are studies demonstrating a concurrent overexpression of VDR and RXRα, partially also describing a worse disease-free survival when RXRα is overexpressed." (PMID 36902107, 2023). "miR-128-2, a pro-apoptotic miRNA was shown to inhibit ABCA1, ABCG1 and RXRα mRNA and protein expression in cell lines such as MCF-7 breast cancer and HepG2 liver hepatocellular carcinoma." (PMID 32577155, 2020). "In breast cancer, DANCR upregulates PI3K/AKT signaling through activating serine phosphorylation of RXRA." (PMID 31804607, 2020). "Recently, we unraveled that Z-10 is a RXRα nitro-ligand with strong growth inhibition and apoptotic induction of MCF-7 breast cancer cells." (PMID 28129653, 2017). "Steroid-Receptors, Heterodimeric-Receptors and the Lipid-sensors, Retinoid-X-Receptors (NR2B1/RXRα, NR2B2/RXRβ, NR2B3/RXRγ) are excluded from our analysis given the wealth of data on their therapeutic significance in breast-cancer." (PMID 26894976, 2016). "We evaluated the effect of etodolac, an FDA-approved NSAID reported to inhibit cyclooxygenase (COX) enzymes and the retinoid X receptor alpha (RXR), on rationally identified potential biomarkers in breast cancer." (PMID 26275572, 2015). "These have been reported to suppress breast cancer development with minimal toxicity compared with RAR-specific ligands, and it was the RXRα isoform that was specifically focused upon in the present study that serves an important role in tumor suppression." (PMID 25778982, 2015). "We examined expression of PPARs, RXRα, and their coactivators SRC-1 and CBP by quantitative RT-PCR in human breast cancer cell lines." (PMID 21080969, 2010).
breast cancer (continued). "Lastly, we demonstrate that the community cohesion scores can predict tamoxifen responses in ER+ breast cancer and suggest potential combination therapies (e.g. NAMPT and RXRA inhibitors) to reduce endocrine therapy resistance based on individualized characteristics." (PMID 38622359, 2024). "Very recently, we found that cytoplasmic colocalization of RXRα and PPARγ, as well as cytoplasmic RXRα itself, are independent negative prognosticators in breast cancer patients." (PMID 37509273, 2023). "For example, higher VD levels were associated with lower methylation of Wnt Family Member 5A (WNT5A) and dickkopf 1 (DKK1) genes in colorectal cancer patients and higher methylation of Retinoid X Receptor Alpha (RXRA) and NAD Synthetase 1 (NADSYN1) genes in breast cancer patients." (PMID 36430854, 2022). "Additionally, the binding of RXRα to HDGF promoter blocked HDGF transcriptional activity, consequently inhibiting breast cancer radioresistance." (PMID 34376200, 2021). "Overexpression of tRXRα but not RXRα in MCF-7 breast cancer cells enhanced AKT activation in vitro and promoted the growth of MCF-7 tumour in animals, which was suppressed when animal were treated with K-80003." (PMID 28714476, 2017). "Though p-values were <0.05 for some tag SNPs and haplotypes in VDR, CYP24A1, and RXRA prior to FDR adjustment, none of the SNPs or haplotypes were significantly associated with breast cancer risk after accounting for FDR." (PMID 26488576, 2015). "This synergistic effect has also been found in liposarcoma and breast cancer cell lines but not in the present study, in spite of the constitutive expression of PPARγ and RXRα in the nuclei of HCC cells." (PMID 15467764, 2004). "Finally, we showed the correlation of the inhibitory effect of RXRα on miR-103 maturation with the positive role of RXRα in Dicer expression and the negative role of RXRα in breast cancer cell migration." (PMID 37735649, 2023). "Furthermore, RXRα agonist, 9cRA, rescued HDGF overexpression-increased the survival fraction and cell proliferation after I.R. Taken together, the present findings demonstrate that HDGF is critical in RXRα suppression of breast cancer radioresistance." (PMID 34376200, 2021). "Notably, the ER-negative breast cancer cell lines, MDA-MB-231 and MDA-MB-435, also expressed RXRα." (PMID 25778982, 2015). "According to the analysis of TCGA database, the expression of RXRA in breast cancer tissues was lower than that in normal tissues, and the expression was lowest in Basal like subtype (mostly TNBC), suggesting that RXRA might play a role in cancer suppression in TNBC." (PMID 40781327, 2025). "Here, we also showed that RXRα was a suppressor in breast cancer progression, indicating from its negative role in the migration of MDA-MB-231 breast cancer cells." (PMID 37735649, 2023).